IL1B (interleukin 1 beta)
Diseases named in the same sentence as IL1B in open-access papers (continued):
Sharing a sentence is not in itself a finding about the gene and the disease.
rheumatoid arthritis (continued). "The NLRP3 inflammasome, plays a critical role in the pathogenesis of rheumatoid arthritis (RA) by activating inflammatory cytokines such as IL1β and IL18." (PMID 39791728, 2024). "In rheumatoid arthritis (RA), IL-1β promotes mitochondrial membrane depolarization and exacerbates the acidosis-induced apoptosis of articular chondrocytes." (PMID 38684668, 2024). "IL-1β is widely recognized as a crucial proinflammatory cytokine responsible for inducing bone and cartilage damage in rheumatoid arthritis (RA)." (PMID 39684587, 2024). "IL-32 induces the production of pro-inflammatory cytokines such as tumor necrosis factor (TNF)-α, IL-1β, IL-6, and IL-8, and IL-32 expression is highly increased in rheumatoid arthritis (RA) patients." (PMID 38675491, 2024). "Apart from inhibition of phosphorylated p65, salicin in the concentration range of 1.2–120 μM promoted nuclear translocation of Nrf2 and HO-1 expression in IL-1β-induced rheumatoid arthritis fibroblast-like synoviocytes (RA-FLSs)." (PMID 36902097, 2023). "Rheumatoid arthritis (RA), a bone disorder that affects both bones and joints, links osteoporosis to bone loss and inflammation enhanced by increased levels of TNF-α, IL-1β, and metalloproteinases." (PMID 38067111, 2023). "It has been shown to improve rheumatoid arthritis by reducing VEGF expression in IL-1β-induced RA-FLS cells by blocking MAPK signaling pathway." (PMID 35069768, 2022). "Biotherapies aimed against pro‐inflammatory cytokines, such as IL‐1β, are currently used against Rheumatoid arthritis (RA) and other inflammasome‐related diseases." (PMID 35438238, 2022). "On the other hand, it seems that IL-1B polymorphisms may not have a clearcut association with rheumatoid arthritis." (PMID 36518750, 2022). "Elevated expression of the CXCL6 gene was observed in OA chondrocytes and FLS-rheumatoid arthritis (FLS-RA) cells stimulated in vitro with IL-1β and resistin (adipokine), respectively." (PMID 36233118, 2022). "Our results agree with other PRGF applications that inhibit the TNFα and IL-1β production by using in vitro rheumatoid arthritis (RA) model." (PMID 36009539, 2022). "Consistently, IRAK1KD synovial fibroblasts showed reduced secretion of neutrophil chemoattractant chemokines following stimulation with IL-1β or human synovial fluids from patients with rheumatoid arthritis (RA) and gout." (PMID 35801586, 2022). "Hence, QLY’s inhibition of IL-1β, IL-6, TNF-α, IL-2 and IFN-γ levels on AA rat serum might be part of the underlying mechanisms for QLY’s anti-rheumatoid arthritis effects." (PMID 34693865, 2021). "The co‐administration of M. Chamomile and A. euchroma, called Marham‐Mafasel, decreases IL‐1β gene expression that leads to a reduction in inflammation in rheumatoid arthritis (RA) animal model." (PMID 33939304, 2021). "Tumor necrosis factor-α (TNF-α) and interleukin-1β (IL-1β) are two cytokines involved in the perpetuation of the chronic inflammation state characterizing rheumatoid arthritis (RA)." (PMID 34201546, 2021). "The co‐administration of M. Chamomile and A. euchroma, called Marham‐Mafasel, decrease IL‐1β gene expression that leads to a reduction in inflammation in rheumatoid arthritis (RA) animal model." (PMID 33939304, 2021). "Feeding Δ9 THC mixed with sesame oil orally to rats with chemically induced rheumatoid arthritis (RA) for 21 days significantly reduced IL-1β concentration to baseline, suggesting the possible inhibition of inflammasomes as a promising target in RA." (PMID 33584697, 2020). "IL-1β is also involved in the osteoclastogenesis and bone resorption, which is augmented in rheumatoid arthritis (RA) joints." (PMID 32668590, 2020). "Cytokines IL-1β and IL-17A are detected in synovial fluid (SF) of rheumatoid arthritis (RA) and OA patients." (PMID 31002692, 2019). "During rheumatoid arthritis (RA), high levels of IL-6, IL1β and GM-CSF were described in the inflamed joints." (PMID 30074983, 2018).
rheumatoid arthritis (continued). "ATP, via P2X7R, induced higher levels of IL-1β in blood samples from rheumatoid arthritis (RA) patients compared to controls." (PMID 29164451, 2018). "Furthermore, IL-1β is also involved in the pathogenesis of many inflammatory diseases such as familial mediterranean fever, familial cold-induced auto-inflammatory syndrome, steroid-resistant asthma, and rheumatoid arthritis." (PMID 29170665, 2017). "Platelet MVs aggravate LPS-induced damage of pulmonary endothelial cells, increase the adhesion of monocytes to endothelial cells, and induce IL-6 and IL-8 in an IL-1β dependent fashion in synovial joints of rheumatoid arthritis (RA) patients." (PMID 28491866, 2017). "Like other pro-inflammatory cytokines such as TNFα and IL-1β, IL-6 is an important therapeutic target of immune disorders, and anti-IL-6 receptor antibody, tocilizumab, has been developed as a therapy in human diseases, including rheumatoid arthritis (RA) and Castleman’s disease." (PMID 27070121, 2016). "IL-1β is involved in the induction and maintenance of chronic inflammation in rheumatoid arthritis (RA)." (PMID 26448682, 2015). "In a previous bivariate analysis, perturbations in serum levels of interleukin-1 beta (IL-1β) and IL-1 receptor antagonist (IL-1ra) were found before onset of clinical rheumatoid arthritis (pre-RA) in women with younger onset ages." (PMID 26693225, 2015). "In vitro assays have confirmed that expression of POSTN and TWIST1 are elevated in fibroblast-like synoviocytes (FLSs) of rheumatoid arthritis patients (RA-FLSs) and are crucial for the migration and invasion of FLSs stimulated with interleukin (IL)-1β." (PMID 25981515, 2015). "A host of proinflammatory cytokines, namely, tumor necrosis factor (TNF-α), IL-1β, and IL-6, are involved in the pathogenesis of rheumatoid arthritis (RA) and are crucial to determine progression of chronic joint inflammation and concomitant bone erosion." (PMID 25784780, 2015). "The increased productions of IL-1β and IL-18 induce renal inflammation and diseases, and excessive IL-6 expression promotes the development and progression of chronic inflammatory diseases, such as, cardiovascular diseases, Alzheimer’s disease, rheumatoid arthritis, and CKD." (PMID 23922826, 2013). "The aim of this study was to determine whether HMGB1 in complex with LPS, interleukin (IL)-1α or IL-1β has enhancing effects on the production of proinflammatory mediators by rheumatoid arthritis synovial fibroblasts (RASF) and osteoarthritis synovial fibroblasts (OASF)." (PMID 21871094, 2011). "The increase production of IL-1β might also mediate the development of abrupt and persistent arthralgia since this cytokine is involved in the immunopathogenesis of many arthritic pathologies such as rheumatoid arthritis." (PMID 19156204, 2009). "In a disease such as rheumatoid arthritis (RA), the pathological roles of pro-inflammatory cytokines such as TNFα, interleukin (IL)-1β, and IL-6 have been demonstrated." (PMID 18493620, 2008). "Leukaemia inhibitory factor, inducible through IL-1β and loaded on the same component together with IL-1β and IL-10, has been shown to have parallels with IL-1, tumour necrosis factor-α and IL-6 within the context of promoting inflammation in rheumatoid arthritis." (PMID 18289371, 2008). "IL-1β and TNF-α are clearly implicated in the pathogenesis of rheumatoid arthritis (RA) since blockage of their activities by antibodies or receptor antagonists is beneficial for patient treatment." (PMID 16846531, 2006). "In rheumatoid arthritis (RA), levels of PC increase in response to inflammatory mediators such as TNF-α, PDGF, and IL-1β." (PMID 40821837, 2025). "Among these, IL-1β, IL-6, and TNF-α play a substantive role in both rheumatoid arthritis and osteoarthritis." (PMID 40491903, 2025). "TGF-β1 induced cytokines, such as TNF–α, IL-1β, IL-1 MIP-1α and MMP-1, in cultured fibroblast-like synoviocytes from rheumatoid arthritis (RA) and osteoarthritis (OA) patients." (PMID 40141345, 2025).
rheumatoid arthritis (continued). "IL‐17 plays a key role in the progression of rheumatoid arthritis in the TMJ, amplifying inflammation by stimulating the release of other pro‐inflammatory cytokines (such as TNF‐α, IL‐6, and IL‐1β), chemokines, and matrix metalloproteinases." (PMID 41006957, 2025). "Diseases that lead to chronic production of IL-1β and TNF-a, such as autoinflammatory syndromes and rheumatoid arthritis, can be a target for Resv, especially considering that the incidence of these conditions increases with age." (PMID 40076963, 2025). "Whereas in rheumatoid arthritis, PVT1 knockdown suppressed IL-1β and IL-6 expression, consistent with our findings of significantly reduced IL-6 expression in the SLE + si-Pvt1 group, while also activating apoptosis in fibroblast-like synoviocytes." (PMID 40493320, 2025). "Rheumatoid arthritis results in an increase in serological biomarkers such as ACPA, CRP, IL-1β, IL-6, and TNF-α." (PMID 40136507, 2025). "Rheumatoid arthritis patients are characterized by elevated levels of pro-inflammatory cytokines such as TNF-α, IL-6, IL-1β, and CRP, which reflect heightened inflammatory activity." (PMID 40709173, 2025). "However, excessive IL-1β activity can lead to chronic inflammation, as seen in rheumatoid arthritis (RA), inflammatory bowel disease (IBD), and atherosclerosis." (PMID 40453076, 2025). "The pathophysiology of rheumatoid arthritis (RA) involves the contribution of cytokines, specifically TNF-α, IL1-β, IL-6, and IL-8, which play significant roles in the process of synovial inflammation and joint destruction by inducing MMP expression." (PMID 38254696, 2024). "In patients with rheumatoid arthritis, dietary supplementation with n-3 PUFA results in significantly decreased IL-1β levels in plasma, and in healthy volunteers, diets enriched in fish oil n-3 PUFA lead to reduced TNF-α and IL-1β levels." (PMID 38892051, 2024). "Anakinra is a recombinant IL-1β antagonist approved by the United States Food and Drug Administration (FDA) for the treatment of rheumatoid arthritis." (PMID 39475614, 2024). "The potential core targets for Mugua treatment of rheumatoid arthritis are IL-6, TNF, IL-1β, and IL-10." (PMID 39705460, 2024). "In patients with rheumatoid arthritis, the administration of n-3 PUFAs for 6 months significantly reduced levels of TNF-α, IL-1β, and prostaglandin E2 from the baseline and increased levels of the anti-inflammatory cytokine IL-10." (PMID 38892051, 2024). "2-DG also blocked signals induced by TNF-α, IL-1β, and interferon (IFN)-γ, efficiently alleviating a mouse model of inflammatory bowel disease and human rheumatoid arthritis." (PMID 38542934, 2024). "Kang and colleagues investigated the role of 3′SL in inflammation connected to rheumatoid arthritis and observed that cotreatment with IL-1β and 3′SL in THP-1 cells also reduced IL-1β, IL-6, and TNF mRNA and protein expression." (PMID 39325548, 2024). "When the human cyclooxygenase-2 gene is silenced on cultured synovial cells of rheumatoid arthritis patients, there is a reduction of prostaglandin E2 (PGE2), vascular endothelial growth factor (VEGF), IL-1β, and TNF-α." (PMID 37446881, 2023). "TNF-α, IL-1β, and IL-6 are potent pro-inflammatory cytokines exerting pleiotropic effects on various cell types and play a critical role in the pathogenesis of chronic inflammatory diseases, such as OA and rheumatoid arthritis (RA)." (PMID 36846635, 2023). "LXA4 inhibited synoviocyte proliferation and also decreased the levels of IL-6, IL-1β, and TNF-α in rheumatoid arthritis." (PMID 37388729, 2023). "In rheumatoid arthritis (RA), CD36 expression in fibroblasts is increased by macrophage-derived inflammatory mediators, including interleukin-1β (IL-1β), IL-6 and interferon gamma (IFN-γ)." (PMID 37576819, 2023).
rheumatoid arthritis (continued). "Notably, high CTRP1 and CTRP6 serum levels are also associated with increased TNF-α, IL-1β, and IL-6 blood concentrations, and CTRP1 and CTRP6 serum levels are increased in patients suffering from chronic inflammatory diseases, such as rheumatoid arthritis and Kawasaki disease." (PMID 37047812, 2023). "More specifically, IL-34 is overexpressed in the inflamed synovium of rheumatoid arthritis patients, where it appears to act synergistic with TNF and IL-1β, inducing osteoclastogenesis and contributing to tissue inflammation and bone erosion." (PMID 35347503, 2023). "For example, in the context of rheumatoid arthritis, HIF-1α was shown to directly interfere with the production of TNF-α, IL-1β, IL-6 and IL-8." (PMID 38273861, 2023). "Therefore, to assess whether the defect in LXR signalling is because of a failure of oxysterol production or signalling, we performed lipidomics on BMDMs treated with a cocktail of inflammatory cytokines associated with rheumatoid arthritis (TNF, GM‐CSF, IL‐1β and IL‐6)." (PMID 37091327, 2023). "In vivo rat model of rheumatoid arthritis (RA), DEX suppresses NLRC5, therefore reducing cytokine levels of IL-1β, IL-6, IL-17A, and TNF-α." (PMID 35628263, 2022). "The exact cause of rheumatoid arthritis (RA) is unknown, but inflammatory mediators such as TNF-α, IL-1β, COX-2, and nitric oxide (NO) are responsible for the destruction of articular cartilage." (PMID 35268651, 2022). "On the other hand, 82 genes were found significantly upregulated in the M-MONO group, including CCL3, IL1B, and several MHC class II genes that were enriched in autoimmune disease pathways (such as rheumatoid arthritis and asthma)." (PMID 35133977, 2022). "Regarding these cytokines, it has been described that IL-1β and TGF-β are common factors in angiogenesis and the proliferation of the synovial fibroblasts in rheumatoid arthritis." (PMID 36611853, 2022). "A variety of pro-inflammatory cytokines (e.g., interleukin-1 beta (IL-1b), tumor necrosis factor-alpha (TNF-a), and IL-6) are known to play prominent roles in the progression of inflammatory diseases such as rheumatoid arthritis, pneumonia, and gout." (PMID 35216342, 2022). "Anakinra is an IL-1β antagonist approved by the U.S. Food and Drug Administration (FDA) for the treatment of rheumatoid arthritis and other autoimmune diseases to reduce clinical symptoms and suppress joint destruction." (PMID 34860273, 2022). "IL-1β, IL-6, IL-8, and TNF-α are involved in the pathogenesis of many inflammatory diseases including rheumatoid arthritis, psoriatic arthritis, and IBD." (PMID 36505430, 2022). "MCC950 ameliorates rheumatoid arthritis injury by inhibiting NLRP3 activation and subsequent IL-1β production." (PMID 35833125, 2022). "However, mycolactone alone can super-induce IL-1β secretion in a well-defined ex vivo model of rheumatoid arthritis (RA), consisting of cultures of synovial membrane cells from RA patients who have undergone elective joint replacement surgery." (PMID 35154073, 2021). "In rheumatoid arthritis, CYR61 was found to be overexpressed in the synovial tissue of patients and was able to induce the expression of IL-6, CCL20, IL-1β, and MMP-3 in cultured fibroblast-like synoviocytes from patients." (PMID 33542676, 2021). "Glucocorticoids decrease IL-1β and TNF-α levels, improving the function of endothelium in rheumatoid arthritis (RA)." (PMID 33868242, 2021). "IAld I3AA inhibited the expression of IL1b and IL6 in an AhR dependent manner, whereas I3AA showed AhR-independent anti-angiogenic activity in cell-based models of rheumatoid arthritis." (PMID 34639632, 2021). "PTX3 expressed by numerous cell types after stimulation with cytokines (e.g. IL-1β and TNF-α), TLR agonists or microbes in inflammation is found to be increased in rheumatoid arthritis synovial fluid." (PMID 33746606, 2021). "In the synovium of rheumatoid arthritis, the content of HIF-1α is increased, which is crucial for IL-1β." (PMID 33995016, 2021).
rheumatoid arthritis (continued). "It is well accepted that macrophages play an essential role in the pathogenesis of inflammatory disease rheumatoid arthritis (RA) by producing pro-inflammatory cytokines like TNF-α, IL-1β, IL-6 that can drive osteoclastogenesis and bone destruction." (PMID 34421899, 2021). "Anakinra, recombinant human IL-1 receptor antagonist, that blocks IL-1α and IL-1β, has been FDA approved for the treatment of rheumatoid arthritis since 2001." (PMID 34749739, 2021). "In rheumatoid arthritis (RA), synoviocytes express the truncated form of Trx-80, and treatment with the proinflammatory cytokines IL-1β and/or TNF-α increases Trx-80 cell expression, playing an important role in the establishment and/or the development of RA autoimmunity." (PMID 35008500, 2021). "In the rheumatoid arthritis synovial fibroblasts (RASFs) of human, the expression level of cPLA2 is increased by proinflammatory cytokines such as TNF-α and IL-1β." (PMID 33796022, 2021). "It has been shown that the methotrexate treatment reduces the TNFα, IL1β, and IL6 production and increases the IL10 expression in the synovial tissue of rheumatoid arthritis patients." (PMID 31958219, 2020). "There are numerous studies on inflammatory cytokines such as IL-1α, IL-1β, and TNF-α in joint disorders, including osteoarthritis, rheumatoid arthritis, posttraumatic osteoarthritis, and hemophilic arthropathy." (PMID 33213419, 2020). "Serum and synovial fluid of patients with rheumatoid arthritis have high amounts of proinflammatory cytokines such as TNF-α, IL-1β, and IL-6." (PMID 32708317, 2020). "As in chondrocytes, EGCG can also suppress the IL-1β-induced MMP-2 and TNF-α-induced MMP-1 and 3 production in rheumatoid arthritis synovial fibroblasts." (PMID 33374730, 2020). "More specifically, it has been demonstrated that the biological action of IL-34 involved in inflammation is mediated through pro-inflammatory cytokines including tumor necrosis factor-alpha (TNF-α) and IL-1β in fibroblast-like synoviocytes (FLS) isolated from rheumatoid arthritis (RA) patients." (PMID 32409720, 2020). "HIF-1α acts as a key regulator during inflammation, increasing pro-inflammatory cytokines (e.g., TNF-α, IL-1β, IL-6, and IL-8), matrix metalloproteinases (e.g., MMP-1, MMP-3, and MMP-9), and pathways of glucose metabolism in rheumatoid arthritis (RA)." (PMID 33374961, 2020). "Transfection of miR-20a mimic reduced the release of IL-6, CXCL10, and IL-1β, as well as TNF-α by rheumatoid arthritis fibroblast-like synoviocytes." (PMID 33584204, 2020). "Many cytokine inhibitors, including those targeting IL‐1β, IL‐6, and TNF‐α, have been approved for the treatment of inflammatory diseases, such as bone destruction and rheumatoid arthritis." (PMID 30414292, 2019). "Ginkgetin reduced arthritic inflammation in rat adjuvant-induced arthritis, while resveratrol showed inhibitory effects on TNF-α-induced IL-1β and MMP-3 production in human rheumatoid arthritis fibroblast-like synoviocytes." (PMID 31757048, 2019). "GA suppresses the expression of several proinflammatory mediators, such as IL-6, IL-1β, CCL2 and CCL7, in fibroblast-like synoviocytes from rheumatoid arthritis patients." (PMID 31026283, 2019). "When transcriptional changes were mapped onto the Rheumatoid Arthritis KEGG pathway, excessive production of IL-1β and TNF by innate leucocytes was identified as a key change, corresponding with the changes observed in mice." (PMID 30552177, 2019). "The collagen-induced arthritis mouse model is known as a human rheumatoid arthritis model and is reported to exhibit mRNA increases in TNF-α, IL-1β, IL-6, and IL-18 during the progression of arthritis." (PMID 29389956, 2018). "In our study, a significant proportion of genes elevated by IL-1B and IL-36 belonged to the KEGG rheumatoid arthritis pathway (e.g., CCL20, CXCL7, and CXCL1)." (PMID 29434599, 2018).